AHNAK (AHNAK nucleoprotein)
Description:
May be required for neuronal cell differentiation.
Synonyms: PM227; MGC5395; AHNAK1; AHNAKRS
Tractability: Antibody: its Gene Ontology location is reachable by antibodies, with high confidence; the Human Protein Atlas places it where antibodies can reach. PROTAC: UniProt records ubiquitination sites on it; ubiquitination databases record sites on it; its protein half-life has been measured.
Gene: Protein-coding gene on chromosome 11 (62,433,542 to 62,556,235, reverse strand). Ensembl gene ENSG00000124942.
Subcellular location: Nucleus
Subcellular location (Human Protein Atlas): Cytosol; Plasma membrane
Gene Ontology:
Molecular function: cadherin binding; protein binding; RNA binding; S100 protein binding; structural molecule activity conferring elasticity
Biological process: positive regulation of plasma membrane repair; regulation of RNA splicing
Cellular component: actin cytoskeleton; cell-cell contact zone; cytoplasm; cytosol; extracellular exosome; focal adhesion; lysosomal membrane; membrane; membrane raft; plasma membrane; plasma membrane protein complex; sarcolemma; vesicle; costamere; nucleus; T-tubule
Genetic constraint (gnomAD): Loss-of-function variants: 23 observed, 41.09 expected, observed/expected ratio (o/e) 0.56, 90% interval 0.4 to 0.79. The upper end of that interval is the gene's LOEUF score, 0.79, which puts it in group 3 of 6, group 1 being the genes least tolerant of losing a copy. Missense variants: 7,411 observed, 7,594.4 expected, observed/expected ratio (o/e) 0.98, 90% interval 0.96 to 1. Synonymous variants: 2,481 observed, 2,658.1 expected, observed/expected ratio (o/e) 0.93, 90% interval 0.9 to 0.96.
Homologues: Orthologues: chimpanzee AHNAK (99% identical), macaque AHNAK (93% identical), dog AHNAK (84% identical), pig AHNAK (84% identical), mouse Ahnak (78% identical), rat Ahnak (73% identical), tropical clawed frog AHNAK (43% identical). Paralogues in human: AHNAK2 (13% identical), PRX (5% identical).
Diseases named in the same sentence as AHNAK in open-access papers:
AHNAK is named in the same sentence as 103 diseases in open-access papers, as found by Europe PMC text mining. Sharing a sentence is not in itself a finding about the gene and the disease. The quoted sentences say what the papers report.
breast carcinoma (21 papers, 2014 to 2025). "It was also found that AHNAK expression was decreased in breast cancer tissues compared to normal tissues, and it was hypothesized that AHNAK may be a tumor suppressor and that its deficiency promoted mammary cell proliferation and tumor development in mice." (PMID 38033502, 2023). "Furthermore, roles in cancer are implicated, and AHNAK has been shown to facilitate EV release in mammary carcinoma cells, therefore playing critical roles in EV communication in the tumor environment." (PMID 32411128, 2020). "One report showed that AHNAK is more highly expressed in vesicles produced by MDA-MB-231 cells from highly invasive breast cancers compared to the less invasive MC7 cells, and appears to be an essential element for vesicle formation." (PMID 38033502, 2023). "The study successfully screened MMTV mice with AHNAK-/- and AHNAK+/+ phenotypes and found that AHNAK-/- mice developed more mammary tumors." (PMID 38033502, 2023). "Mutant plectin (PLEC), marker Of Proliferation Ki-67 (MKI67), HEAT Repeat Containing 1 (HEATR1) and AHNAK nucleoprotein (AHNAK) were detected in three of the four breast cancer cell lines." (PMID 33274046, 2020). "AHNAK has been described as a tumor suppressor in breast cancer that negatively regulates both the AKT/MAPK and Wnt/β-catenin signaling pathways." (PMID 32156068, 2020). "For instance, AHNAK negatively regulates cell growth via TGF-β signaling as a tumor suppressor in breast cancer." (PMID 30836988, 2019). "AHNAK has been shown to enable EV release from mammary carcinoma cells, playing critical roles in EV communication for promotion of cancer progression in the tumour microenvironment." (PMID 30597867, 2018). "Meanwhile, compared with the other subtypes of breast cancer, the basal-like subtype has the lowest average AHNAK expression." (PMID 28494797, 2017). "Among 20 common types of tumours, 12 tumour types exhibited decreases in AHNAK expression, including breast cancer." (PMID 28494797, 2017). "Although several proteins have been identified to interact with AHNAK, the function of AHNAK in breast cancer remains undefined." (PMID 28494797, 2017). "To further explore the expression of AHNAK in breast cancer, we tested the level of AHNAK mRNA in a panel of 10 breast cell lines, including 8 human breast cancer cell lines and 2 normal mammary epithelial cell lines using a qRT-PCR method." (PMID 28494797, 2017). "Quantitation of these data indicates that AHNAK expression was significantly higher in mammary carcinoma cells than normal epithelium." (PMID 27374178, 2016). "Taken together, our results indicate that AHNAK enables mammary carcinoma cells to form and release extracellular vesicles that travel into recipient fibroblasts." (PMID 27374178, 2016). "Confocal microscopy was used to examine the expression of AHNAK in mammary carcinoma cells and vesicles." (PMID 27374178, 2016). "Here, we investigated the role of AHNAK in extracellular vesicle formation and exchange between mammary carcinoma cells and neighboring fibroblasts." (PMID 27374178, 2016). "For example, two recent studies have reported a significant gene-drug correlation between AHNAK expression and chemotherapy compounds, including paclitaxel, docetaxel, erlotinib, everolimus, and doxorubicin in breast cancer." (PMID 26089344, 2015). "However, the role of AHNAK in cancer appears to be tissue-specific, as other reports also point to a potential role as a tumor suppressor in glioma and breast cancer." (PMID 34202325, 2021). "Interestingly, in melanoma, breast cancer, gastric cancer, and lung cancer, AHNAK acted as a suppressor in regulation of tumor progression." (PMID 32904605, 2020). "We, therefore, sought to investigate the role of AHNAK in mammary carcinoma extracellular vesicles." (PMID 27374178, 2016).
breast carcinoma (continued). "Thus, AHNAK appears to promote extracellular vesicle production by mammary carcinoma cells in order to increase fibroblast migration with consequent modification of the tumor microenvironment." (PMID 27374178, 2016). "However, some studies have suggested the opposite that AHNAK is a suppressor in breast cancer." (PMID 38033502, 2023). "In addition, it remains unclear whether the proposed role for AHNAK is limited to only the triple-negative subtype of breast cancer." (PMID 28494797, 2017). "SORBS1 overexpression promoted CRC growth and migration via inhibition of AHNAK expression, while SORBS1 was downregulated in breast cancer and led to poor prognosis." (PMID 34409913, 2021). "In the present study, we demonstrated that AHNAK mRNA levels were down-regulated in 7 out of 8 human breast cancer cell lines, especially in triple - negative breast cancer (TNBC) cell lines." (PMID 28494797, 2017). "We found that depletion of AHNAK by siRNA did not affect mammary carcinoma cell growth in vitro, but inhibited the ability of these cells to produce microvesicles." (PMID 27374178, 2016). "We also found that AHNAK did not affect cell proliferation or viability of these cells, indicating that AHNAK expression was not critical for mammary carcinoma cell growth." (PMID 27374178, 2016). "Interestingly, an abundance of AHNAK and annexin A2 were found in extracellular vesicles released by mammary cancer cells towards non-cancer mammary fibroblasts, indicating a role for AHNAK in vesicular communication promoting cancer progression." (PMID 35158796, 2022). "The results of a recent study using a transgenic mouse model of breast cancer and human breast cancer samples suggest that AHNAK can act as a tumour suppressor that mediates the negative regulation of cell growth via the modulation of the TGFβ/Smad signalling pathway." (PMID 28494797, 2017). "However, the functional relevance of AHNAK in mammary carcinoma derived vesicles has not been elucidated." (PMID 27374178, 2016).
bladder cancer (14 papers, 2020 to 2026). "Future studies are needed to characterize the biology function of the associations between mutations in SMGs or pathways and mutational signature activities to establish the potential of utilizing the mutated genes such as AHNAK as biomarkers for the clinical management of bladder cancer patients." (PMID 36495164, 2023). "Notably, we identified that the APOBEC‐a signature activity, an indicator of good clinical outcome in bladder cancer, was associated with AHNAK mutations which appeared to regulate the TGFβ signaling in a previous study at the protein level." (PMID 36495164, 2023). "The EdU, Transwell Invasion, and wound healing assays collectively demonstrated that AHNAK knockdown significantly suppressed bladder cancer cell proliferation, migration, and invasion." (PMID 41505248, 2026). "Previous analyses revealed that AHNAK exhibited the strongest correlation with bladder cancer among the prognostic genes, prompting its selection for subsequent investigations." (PMID 41505248, 2026). "We found that knockdown of AHNAK reduced the proliferation, migration, and invasion abilities of bladder cancer cells and also promoted cell apoptosis." (PMID 41505248, 2026). "Previous studies have demonstrated that NAT10 promotes cisplatin resistance in bladder cancer by indirectly facilitating DNA damage response (DDR) through post-transcriptional regulation of AHNAK mRNA stability." (PMID 40908816, 2025). "Previous study found that NAT10 drove the cisplatin resistance by promoting the mRNA stability of AHNAK in bladder cancer." (PMID 39085201, 2024). "Studies have found that NAT10 promotes cisplatin resistance in bladder cancer by enhancing AHNAK-mediated DNA damage repair." (PMID 39742262, 2024). "NAT10‐mediated ac4C acetylation of AHNAK promotes cisplatin resistance in bladder cancer by activating the AHNAK‐mediated DNA damage repair pathway." (PMID 39640362, 2024). "Numerous studies have reported a significant upregulation of AHNAK expression in bladder cancer tissues." (PMID 38103068, 2023). "As for AHNAK, two studies have conducted prognosis model analyses with this and other bladder cancer genes, and both showed poor outcomes with high levels of AHNAK expression." (PMID 33465047, 2021). "Moreover, apoptosis assays revealed that the depletion of AHNAK enhanced apoptosis in bladder cancer cells." (PMID 41505248, 2026). "AHNAK is involved in cell adhesion, migration, and metastasis in bladder cancer." (PMID 38103068, 2023). "The specific functional and molecular roles of AHNAK in bladder cancer are still unknown." (PMID 38103068, 2023). "The expression of AHNAK was also found to be significantly decreased in BLCA compared to BUL, which is consistent with the results in the TCGA database, suggesting that AHNAK may be a suppressor gene and diagnostic marker for bladder cancer." (PMID 38033502, 2023). "To investigate the effects of AHNAK and NFATC1 on the biological functions of bladder cancer cells, we performed transwell and MTT assays." (PMID 35958586, 2022). "From the current studies, it appears that AHNAK may play different roles in different tumors, even though within the same tumor its role is controversial, such as TNBC, melanoma and bladder cancer." (PMID 38033502, 2023). "Therefore, we experimentally validated the functions related to EMT, glycolysis, glutamine metabolism and immune checkpoint regulation of AHNAK and NFATC1 in bladder cancer." (PMID 35958586, 2022).
gastric cancer (14 papers, 2017 to 2024). A primary or metastatic malignant neoplasm involving the stomach. "Studies have shown that AHNAK is associated with colorectal cancer, ovarian cancer, gastric cancer and other diseases." (PMID 35574315, 2022). "AHNAK has been demonstrated as one of the cancer driver genes to participate in the tumorigenesis and progression of various malignancies, such as gastric cancer, prostate adenocarcinoma, and laryngeal cancer." (PMID 34368222, 2021). "Previous studies suggested that regulating AHNAK expression could affect epithelial-mesenchymal transitions (EMT) in gastric cancer by regulating the Wnt signaling pathway." (PMID 35954405, 2022). "In addition, miR-93-5p (a member of the miR-106b-25 cluster) positively affects cell proliferation and the migration of gastric cancer cells via directly targeting AHNAK nucleoprotein (AHNAK), which is a negative regulator of the EMT process." (PMID 33066509, 2020). "Additionally, OMT restrained gastric cancer cell progression via mediating miR-93-5p/AHNAK axis." (PMID 35609310, 2022). "Most interestingly, AHNAK has been reported to be associated with enhanced proliferation and migration in rhabdomyosarcoma among other cancers as well as supporting EMT in hepatoblastoma, endometrial and lung cancer cells as well as pancreatic ductal adenocarcinoma and gastric cancer." (PMID 34202325, 2021). "In gastric cancer, through its interaction with APC, it negatively regulates canonical WNT signaling, therefore acting as a tumor suppressor similarly to AHNAK." (PMID 38918490, 2024). "Studies have shown that upregulation of MicroRNA-93-5p suppressed AHNAK expression, which activated the Wnt signaling pathway and promoted EMT, proliferation, and migration of gastric cancer cells." (PMID 38033502, 2023). "The MYOF, CLIP1, AHNAK, ANXA2, ITPRIPL2 and LEPROT genes in tissues of patients with gastric cancer were found to be altered by amplification, extensive deletion, truncating mutations, splice mutations, missense mutations, and high/low mRNA expression." (PMID 36147922, 2022). "In contrast, overexpression of AHNAK inhibited the migration, invasion and EMT of gastric cancer HGC-27 cells, which indicates that AHNAK may act as a suppressor to regulate the progression of gastric cancer." (PMID 38033502, 2023).
lung carcinoma (10 papers, 2013 to 2024). "Downregulation of AHNAK has previously been observed in ovarian cancer, lung cancer, brain tumor and BC." (PMID 39165691, 2024). "AHNAK has also been reported to enhance metastasis in lung cancer and mesothelioma." (PMID 36557813, 2022). "Collectively, AHNAK, COL11A1, and COL6A3 may be potential candidates for therapeutic and diagnostic biomarkers in head and neck cancer and lung carcinoma." (PMID 26352260, 2015). "While the role of AHNAK in lung adenocarcinoma remains controversial, several studies have now confirmed the role of AHNAK2 as a pro-cancer factor in lung cancer." (PMID 38033502, 2023).
melanoma (10 papers, 2016 to 2023). A malignant, usually aggressive tumor composed of atypical, neoplastic melanocytes. "AHNAK is downregulated and remarkably linked with poor survival in numerous cancers, such as glioma and melanoma." (PMID 34689136, 2021). "High AHNAK in pancreatic ductal adenocarcinoma (PDAC) was associated with short survival; however, in melanoma low AHNAK was associated with poor prognosis, suggesting a tumor-specific role of AHNAK in prognosis." (PMID 32733809, 2020). "Recently, a report suggested that the knockdown of AHNAK in a melanoma cell line led to the loss of cadherin-1 and was associated with poor patient outcomes, providing evidence that upregulated RNF38 induced a reduction in E-cadherin levels rather than directly interacting with E-cadherin." (PMID 30836988, 2019). "The role of AHNAK in melanoma development still appears to be controversial and needs to be further investigated." (PMID 38033502, 2023). "Another study noted that AHNAK expression was significantly downregulated in melanoma and correlated with poor prognosis, and that knockdown of AHNAK in primary melanocytes resulted in reduced expression of E-calcineurin." (PMID 38033502, 2023). "Immunoreaction to AHNAK has mainly been observed in the cytoplasm of normal cells compared with melanoma and bladder urothelial carcinoma cells, whereas high levels of AHNAK have been shown to predict a poor outcome in PDAC, HCC and laryngeal carcinoma." (PMID 36557813, 2022).
glioma (9 papers, 2017 to 2024). A benign or malignant brain and spinal cord tumor that arises from glial cells (astrocytes, oligodendrocytes, ependymal cells). "Overexpression of AHNAK in U87 and U251 cells inhibited the proliferation and invasion of glioma cells and induced apoptosis." (PMID 38033502, 2023). "A previous study reported that overexpression of AHNAK inhibited glioma cell proliferation, invasion, Ki67 expression, and induced apoptosis." (PMID 34721590, 2021). "The expression of AHNAK was found to be lesser in GSC compared to DGC suggestive of a cancer stem cell inhibitory function in glioma." (PMID 28035070, 2017). "Additionally, an analysis of the regulatory mechanisms that contribute to cancer development has revealed that subclonal mutations of AHNAK and AHNAK2 in GBM can impact crucial molecules and processes linked to glioma progression." (PMID 38166029, 2024). "In addition, 30 normal brain tissue and 73 glioma tissue specimens were collected in this study, which confirmed that the low expression of AHNAK in glioma was correlated with poor prognosis." (PMID 38033502, 2023). "It has been shown that the mRNA levels of AHNAK were downregulated in glioma and may be an independent prognostic factor for poor survival of glioma patients." (PMID 35496054, 2022). "By analyzing the regulatory mechanisms underlying the risk subclonal mutations, we found that the subclonal mutations of AHNAK and AHNAK2 in GBM and those of NF1 and PTEN in LGG could influence some important molecules and functions associated with glioma progression." (PMID 35496054, 2022). "Although the AHNAK transcript levels was found to be similar in GBM compared to control brain samples, we found a significantly lower level in GSCs when compared to the differentiated glioma cells (DGCs)." (PMID 28035070, 2017).